RPS27L (ribosomal protein S27 like)
Tractability: PROTAC: ubiquitination databases record sites on it; its protein half-life has been measured.
Gene: Protein-coding gene on chromosome 15 (63,125,872 to 63,158,021, reverse strand). Ensembl gene ENSG00000185088.
Subcellular location (Human Protein Atlas): Cytosol; Endoplasmic reticulum; Nucleoli
Pathways (Reactome):
Metabolism of proteins: Eukaryotic Translation Termination; Formation of a pool of free 40S subunits; Formation of the ternary complex, and subsequently, the 43S complex; GTP hydrolysis and joining of the 60S ribosomal subunit; L13a-mediated translational silencing of Ceruloplasmin expression; PELO:HBS1L and ABCE1 dissociate a ribosome on a non-stop mRNA; Peptide chain elongation; Ribosomal scanning and start codon recognition; SRP-dependent cotranslational protein targeting to membrane; Translation initiation complex formation; ZNF598 and the Ribosome-associated Quality Trigger (RQT) complex dissociate a ribosome stalled on a no-go mRNA
Disease: SARS-CoV-1 modulates host translation machinery; SARS-CoV-2 modulates host translation machinery; Viral mRNA Translation
Metabolism of RNA: Major pathway of rRNA processing in the nucleolus and cytosol; Nonsense Mediated Decay (NMD) enhanced by the Exon Junction Complex (EJC); Nonsense Mediated Decay (NMD) independent of the Exon Junction Complex (EJC)
Cellular responses to stimuli: Response of EIF2AK4 (GCN2) to amino acid deficiency
Developmental Biology: Regulation of expression of SLITs and ROBOs
Metabolism: Selenocysteine synthesis
Gene Ontology:
Molecular function: protein binding; RNA binding; translation activator activity; structural constituent of ribosome
Biological process: mitotic G1 DNA damage checkpoint signaling; positive regulation of translation; rRNA processing; translation
Cellular component: cytosol; endoplasmic reticulum; nucleolus; nucleus; cytosolic small ribosomal subunit; ribosome
Genetic constraint (gnomAD): Loss-of-function variants: 2 observed, 2.14 expected, observed/expected ratio (o/e) 0.94, 90% interval 0.35 to 1.86. That is too few expected variants to judge how well the gene tolerates losing a copy. Missense variants: 24 observed, 21.91 expected, observed/expected ratio (o/e) 1.1, 90% interval 0.79 to 1.54. Synonymous variants: 7 observed, 7.16 expected, observed/expected ratio (o/e) 0.98, 90% interval 0.55 to 1.73.
Homologues: Orthologues: macaque RPS27L (100% identical), mouse Rps27l (100% identical), pig RPS27L (100% identical), rabbit RPS27L (100% identical), rat Rps27l (98% identical), dog RPS27L (92% identical), zebrafish rps27l (90% identical). Paralogues in human: RPS27 (96% identical).
Diseases named in the same sentence as RPS27L in open-access papers:
RPS27L is named in the same sentence as 30 diseases in open-access papers, as found by Europe PMC text mining. Sharing a sentence is not in itself a finding about the gene and the disease. The quoted sentences say what the papers report.
breast carcinoma (5 papers, 2018 to 2023). "The knockdown of RPS27L induces autophagy in breast cancer MB231 and SK-BR3 cells by shortening the protein half-life of β-TrCP which is involved in the degradation of DEPTOR, the natural inhibitor of mTOR." (PMID 34873618, 2021). "The blockage of autophagy induced by RPS27L leads to the regression of breast cancer cell growth by triggering apoptosis." (PMID 34873618, 2021). "It is worth noting that in this study, 8 (ACTR3, ARF4, PGRMC1, RPS23, WDR12, ACTR2, SIAH1, and RPS27L) of 12 hub genes are related to cancers, such as lung cancer, epithelial ovarian cancer, gastric cancer, glioblastoma, breast cancer, and esophageal cancer." (PMID 33391181, 2020). "Collectively, these results demonstrated that RPS27L silencing readily induces autophagy in breast cancer cells." (PMID 30425236, 2018). "In our study, blockage of autophagy induced by RPS27L silencing significantly inhibits the growth of breast cancer cell via the induction of apoptosis, indicating that autophagy plays a survival role in response to stress triggered by RPS27L deficiency." (PMID 30425236, 2018). "The statistical analysis by t-test between TPM data of breast carcinoma tissues (n = 1097) and normal tissues (n = 114) showed that the levels of RPS27L expression were significantly downregulated in breast carcinoma." (PMID 30425236, 2018). "In this study, we report RPS27L silencing significantly induced autophagy in breast cancer cells as well as mouse fibroblasts by selectively inactivating mTORC1." (PMID 30425236, 2018). "Similarly, the silencing of RPS27L led to autophagy in mouse fibroblasts and human breast cancer cells via the inhibition of S6K1 phosphorylation and mTOR Complex1 activity." (PMID 36616305, 2023). "Other RPs are found to be down-regulated in breast cancer including RPS27L." (PMID 34873618, 2021). "Taken together, abrogation of autophagy induced by RPS27L depletion enhances cell killing via induction of apoptosis, suggesting that autophagy triggered by RPS27L silencing is a cellular survival response of breast cancer cells." (PMID 30425236, 2018). "Finally, RPS27L levels were reduced in human breast cancers, as compared to adjacent normal tissues." (PMID 30425236, 2018). "Finally, RPS27L level was significantly reduced in human breast cancer tissues." (PMID 30425236, 2018). "However, whether and how RPS27L acts as a tumor suppressive or tumor promoting factor in breast cancer is previously unknown." (PMID 30425236, 2018). "Thus, our study suggest abrogation of autophagy by autophagy inhibitors, which is considered as an attractive approach for breast cancer therapy, may have therapeutic value in the treatment of breast cancer patients with low RPS27L expression." (PMID 30425236, 2018). "We further extended the findings in breast cancer cells to normal MEF cells, by using two independent pairs of Rps27l+/+ vs. Rps27l−/− MEFs15, and found that Rps27l−/− MEFs had reduced basal phosphorylation levels of S6K1 and 4E-BP1." (PMID 30425236, 2018). "We therefore determined potential alterations of RPS27L levels in breast cancer tissues, as compared to adjacent normal tissues." (PMID 30425236, 2018). "We found that RPS27L silencing remarkably inhibited the activity of mTORC1, but not mTORC2, in breast cancer cells and MEFs, as evidenced by reduced phosphorylation levels of their downstream effectors as well as direct in vitro kinase activity assays." (PMID 30425236, 2018).
colorectal cancer (4 papers, 2013 to 2021). A primary or metastatic malignant neoplasm that affects the colon or rectum. "Moreover, reduced RPS27L expression in either feces or colorectal cancer tissues was also significantly associated with poor survival of patients with colorectal cancer." (PMID 33051438, 2020). "The correlation of RPS27L expression with human cancer was also reported in colorectal cancer, in which low expression of RPS27L in either feces or cancer tissues was related to a worse patient prognosis." (PMID 30425236, 2018). "Finally, a role of RPS27-like (RPS27L) in DNA repair has emerged by the findings showing the reduced expression of two double-strand break repair protein, RAD51 and protein kinase, DNA-activated, catalytic polypeptide (PRKDC) in conditions of RPS27L knockdown in colorectal cancer cells." (PMID 34071057, 2021).
lymphoma (3 papers, 2014 to 2018). A malignant (clonal) proliferation of B- lymphocytes or T- lymphocytes which involves the lymph nodes, bone marrow and/or extranodal sites. "Interestingly, precisely the opposite pattern is observed when comparing RPS29 and RPS27L expression in cell-line models of lymphoma/lymphoid leukemia, which represent intermediate developmental stages, and mature lymphocytes." (PMID 27884178, 2016).
breast tumors (2 papers, 2018 to 2020). "Collectively, the expression of RPS27L is decreased in breast tumors, suggesting that the reduction of RPS27L expression could play a role in breast tumorigenesis." (PMID 30425236, 2018). "Thus, RPS27L staining intensity was lower in breast tumors, as compared to normal breast tissues." (PMID 30425236, 2018). "In the present study, by immunohistochemistry analysis of breast tissue microarray and statistical analysis of TCGA transcriptome data, we showed that the expression of RPS27L was also lower in breast tumors than in normal breast tissues, suggesting it may play a role in breast tumorigenesis." (PMID 30425236, 2018).
colon cancer (2 papers, 2014 to 2024). "Overexpression of RPS27L in LoVo colon cancer cells enhances DNA repair capacity and inhibits apoptosis." (PMID 38542474, 2024). "Potential tumor suppressive function of RPS27L is further supported by an observation that high level of RPS27L expression predicted a better prognosis in colon cancer patients." (PMID 25144937, 2014). "Thus, our study provides an in vivo demonstration that Rps27l is required for the maintenance of genomic stability, which is consistent with a previous report, showing that RPS27L knockdown in HCT116 colon cancer cells may trigger genomic instability." (PMID 25144937, 2014).
lung carcinoma (2 papers, 2020). "Here we reported that RPS27L also regulates ICL repair via stabilization of FANCD2 and FANCI in lung cancer cells." (PMID 33051438, 2020). "RPS27L knockdown, therefore, impaired ICL repair and enhanced the sensitivity of lung cancer cells to ICL-inducing agent MMC." (PMID 33051438, 2020). "Biologically, RPS27L knockdown suppresses FANCD2 foci formation and impairs ICL repair upon exposure to ICL-inducing agent mitomycin C (MMC) in lung cancer cells." (PMID 33051438, 2020). "Given that RPS27L knockdown increases the sensitivity of lung cancer cells to MMC, and RPS27L expression is reduced in NSCLC tissues, our study suggests that ICL-inducing chemotherapeutic agents may have better therapeutic efficacy in the treatment of NSCLC patients with low RPS27L expression." (PMID 33051438, 2020).
thyroid cancer (2 papers, 2016 to 2021). "Among these, RPL26L1 and RPS27L were exclusively up-regulated in breast and thyroid carcinomas, respectively, whereas RPL21 had decreased expression in breast and uterine cancers." (PMID 27884178, 2016). "However, the stable mutation status of RPS27L and IFIT3 together with their high expression in tumor tissues makes them potential biomarkers as well as therapeutic targets in thyroid cancer." (PMID 33711033, 2021). "In addition, our study of IFIT3 implies its great potential in thyroid cancer progressing which has not been reported yet, and these RBPs especially RPS27L and IFIT3 may also be used in clinical adjuvant therapy." (PMID 33711033, 2021).
anemia (1 paper, 2021). A reduction in the number of red blood cells, the amount of hemoglobin, and/or the volume of packed red blood cells. "More recently, it has been reported that in lung cancer cells, RPS27L physically binds Fanconi anemia group D2 (FANCD2) and Fanconi anemia group I (FANCI), two proteins involved in DNA damage and repair." (PMID 34071057, 2021).
deficiencies (1 paper, 2016). "Similarly, RP genes with myeloid-lineage specificity in our analysis, such as RPS27L, RPS15, and RPS24, have been previously implicated in bone marrow deficiencies." (PMID 27884178, 2016).
Fanconi anemia (1 paper, 2020). Fanconi anemia (FA) is a hereditary DNA repair disorder characterized by progressive pancytopenia with bone marrow failure, variable congenital malformations and predisposition to develop hematological or solid tumors. "In summary, we reported here a novel connection between a ribosomal protein and Fanconi anemia proteins, demonstrating that RPS27L binds to and stabilizes FANCD2 and FANCI." (PMID 33051438, 2020). "Here we identified that RPS27L binds to FANCD2 and FANCI, two Fanconi anemia (FA) proteins functioning in ICL repair pathway." (PMID 33051438, 2020).
head and neck carcinoma (1 paper, 2011). A carcinoma that arises from the head and neck region.
Li-Fraumeni syndrome (1 paper, 2014).
osteosarcoma (1 paper, 2021). A usually aggressive malignant bone-forming mesenchymal neoplasm, predominantly affecting adolescents and young adults. "Our results showed that compared with osteoblasts, CPEB3, EIF4E3, RBM34, RPS27L, RPS29 and TDRD6 were down-regulated in U2OS and 143B, while NXT2, TERT, TLR8 and ZC3HAV1 were up-regulated in osteosarcoma cells." (PMID 34926575, 2021).
Sepsis (1 paper, 2025). Sepsis is defined as life-threatening organ dysfunction caused by a dysregulated host response to infection. "The calibration plots showed that the nomogram model composed of 3 genes, GADD45A, HMGB2, and RPS27L, exhibited good diagnostic prediction for sepsis." (PMID 39889168, 2025). "In conclusion, we used machine learning algorithms to identify 3 key DDR-related genes, GADD45A, HMGB2, and RPS27L, which exhibit a good diagnostic impact on sepsis." (PMID 39889168, 2025). "Importantly, we identified 3 pivotal genes, including GADD45A, HMGB2, and RPS27L, which exhibited good diagnostic prediction for sepsis." (PMID 39889168, 2025). "Three different expressed DDR-related genes (GADD45A, HMGB2, and RPS27L) were identified as sepsis biomarkers." (PMID 39889168, 2025).
tumor (13 papers, 2013 to 2025). "The immunoblot analyses confirmed in P3 tumours the up‐regulation of OPN and SERPINA 1, whereas the expression of HDAC2, SRSF3 (spliceosome) and RPS27L (ribosome) was down‐regulated in this type of tumours." (PMID 31560832, 2019). "One of the ribosomal proteins, ribosomal protein S27-like (RPS27L), was reported to be downregulated in feces and tumor tissues of some late-stage CRC patients." (PMID 23826192, 2013). "Collectively, it appears that RPS27L downregulation during breast tumorigenesis could serve as a survival signal to facilitate tumor formation." (PMID 30425236, 2018). "Thus, RPS27L might play a tumor suppressive role in breast tumorigenesis by inhibiting autophagy." (PMID 30425236, 2018). "We found that RPS27L mRNA was also remarkably decreased in non-small cell lung cancer (NSCLC) tissues, which correlated with poor differentiation, indicating a potential tumor-suppressive role of RPS27L in NSCLC." (PMID 33051438, 2020).
cancer (12 papers, 2011 to 2025). A tumor composed of atypical neoplastic, often pleomorphic cells that invade other tissues. "For example, the level of RPS27L in feces is positively correlated with cancer tissue, which can be used as a potential biomarker for early diagnosis." (PMID 34355024, 2021). "Interestingly, LIN28A is associated with specific ribosomal proteins in an RNA-independent mode, and several of these proteins, such as RPL5, RPL10, and RPS27L, have been shown to promote tumorigenesis or cancer." (PMID 34816099, 2021).
RPS27L also shares sentences with these, for which no sentence is quoted: Ad- (1 paper); B-cell lymphomas (1); cervical cancer (1); COVID-19 (1); epithelial ovarian cancer (1); esophageal cancer (1); gastric cancer (1); glioblastoma (1); hepatitis B (1); hepatitis C (1); infection (1); lymphoid leukemia (1); measles (1); uterine cancer (1).